FOXL2 (forkhead box L2)
Description:
Transcriptional regulator. Critical factor essential for ovary differentiation and maintenance, and repression of the genetic program for somatic testis determination. Prevents trans-differentiation of ovary to testis through transcriptional repression of the Sertoli cell-promoting gene SOX9 (By similarity). Has apoptotic activity in ovarian cells. Suppresses ESR1-mediated transcription of PTGS2/COX2 stimulated by tamoxifen (By similarity). Is a regulator of CYP19 expression (By similarity). Participates in SMAD3-dependent transcription of FST via the intronic SMAD-binding element (By similarity). Is a transcriptional repressor of STAR. Activates SIRT1 transcription under cellular stress conditions. Activates transcription of OSR2.
Synonyms: BPES1; BPES; PFRK; PINTO; POF3
Tractability: PROTAC: UniProt records ubiquitination sites on it; ubiquitination databases record sites on it.
Gene: Protein-coding gene on chromosome 3 (138,944,224 to 138,947,137, reverse strand). Ensembl gene ENSG00000183770.
Subcellular location: Nucleus
Subcellular location (Human Protein Atlas): Nucleoplasm
Pathways (Reactome):
Developmental Biology: Transcriptional regulation of testis differentiation
Metabolism of proteins: SUMOylation of transcription factors
Gene Ontology:
Molecular function: cysteine-type endopeptidase regulator activity involved in apoptotic process; DNA binding; protein binding; sequence-specific double-stranded DNA binding; ubiquitin conjugating enzyme binding; DNA-binding transcription factor activity; DNA-binding transcription factor activity, RNA polymerase II-specific; RNA polymerase II cis-regulatory region sequence-specific DNA binding; DNA-binding transcription activator activity, RNA polymerase II-specific; nuclear estrogen receptor binding; sequence-specific DNA binding
Biological process: apoptotic DNA fragmentation; extraocular skeletal muscle development; negative regulation of DNA-templated transcription; ovarian follicle development; positive regulation of apoptotic process; anatomical structure morphogenesis; cell differentiation; positive regulation of DNA-templated transcription; regulation of transcription by RNA polymerase II; embryonic eye morphogenesis; oocyte growth; positive regulation of transcription by RNA polymerase II; regulation of DNA-templated transcription
Cellular component: nucleoplasm; nucleus; chromatin
Genetic constraint (gnomAD): Loss-of-function variants: 3 observed, 2.3 expected, observed/expected ratio (o/e) 1.31, 90% interval 0.52 to 1.91. That is too few expected variants to judge how well the gene tolerates losing a copy. Missense variants: 477 observed, 431.76 expected, observed/expected ratio (o/e) 1.1, 90% interval 1.02 to 1.19. Synonymous variants: 288 observed, 201.23 expected, observed/expected ratio (o/e) 1.43, 90% interval 1.3 to 1.58.
Cancer hallmarks: proliferative signalling (promotes); suppression of growth (promotes); escaping programmed cell death (suppresses); genome instability and mutations (suppresses); invasion and metastasis (promotes); tumour promoting inflammation (promotes); invasion and metastasis (suppresses)
Homologues: Orthologues: macaque FOXL2 (99% identical), mouse Foxl2 (96% identical), rat Foxl2 (96% identical), tropical clawed frog foxl2 (59% identical), zebrafish foxl2a (57% identical), zebrafish foxl2b (53% identical), Drosophila melanogaster slp1 (23% identical), Caenorhabditis elegans pes-1 (18% identical). Paralogues in human: FOXC1 (27% identical), FOXC2 (26% identical), FOXS1 (25% identical), FOXD1 (25% identical), FOXE1 (24% identical), FOXD2 (24% identical), FOXL1 (23% identical), FOXE3 (23% identical), FOXD4L3 (23% identical), FOXD4L5 (23% identical), FOXD4L6 (23% identical), FOXD4 (22% identical), and 29 more.
Diseases named in the same sentence as FOXL2 in open-access papers:
FOXL2 is named in the same sentence as 133 diseases in open-access papers, as found by Europe PMC text mining. Sharing a sentence is not in itself a finding about the gene and the disease. The quoted sentences say what the papers report.
granulosa cell tumor (57 papers, 2009 to 2026). A slow-growing, malignant tumor, characterize by the presence of granulosa-like cells and Call-Exner bodies, that is almost always found in the ovary. "Well over 90% of ovarian adult granulosa cell tumours harbour a recurrent gain‐of‐function FOXL2 mutation (p.C134W), and tumours that lack this alteration can often be re‐classified upon re‐review of their histopathologic features." (PMID 41384702, 2026). "Recent developments in molecular profiling have shown that more than 90% of adult granulosa cell tumors harbor FOXL2 mutations, and more than 90% of Sertoli-Leydig cell tumors have DICER1 mutations." (PMID 39958081, 2025). "FOXL2 mutations have been implicated in various ovarian disorders, including premature ovarian failure and granulosa cell tumors." (PMID 37829050, 2023). "FOXL2 mutations are frequently found in adult granulosa cell tumors, a rare subtype of ovarian cancer." (PMID 37958970, 2023). "FOXL2 (C134W) mutation is highly frequent in adult granulosa cell tumours (95–97%), increasing the induction of aromatase, a known target of FOXL2." (PMID 36399188, 2023). "Mutations in FOXL2 can lead to dysregulated gene expression and cell growth in granulosa cell tumors." (PMID 37958970, 2023). "In the case of luteinized changes in a thecoma, a thecoma with minor sex cord elements, or a thecoma with equivocal/ambiguous reticulin stain, the identification of a FOXL2 variant would favor the diagnosis of an adult granulosa cell tumor." (PMID 38136408, 2023). "Recently, in vivo studies demonstrated that the somatic variant c.402C > G (p.C134W) of FOXL2 was necessary and sufficient to trigger the genesis of adult granulosa cell tumors." (PMID 38136408, 2023). "Previous studies have reported the presence of somatic FOXL2 mutation in granulosa cell tumors in 94–97% of cases." (PMID 36139639, 2022). "Thirdly, a low frequency of FOXL2 mutations in the granulosa cell tumors was observed in this study." (PMID 36139639, 2022). "To determine the potential translational value of our mouse model, we compared our DE genes with those associated with human granulosa cell tumor development or FOXL2 mutation." (PMID 35565312, 2022). "In fact, the causative effects of FOXL2 misregulations have been identified in many ovarian diseases, such as primary ovarian insufficiency and granulosa cell tumor; however, the mechanism by which FOXL2 expression is regulated is not well studied." (PMID 36424497, 2022). "Adult granulosa cell tumors (AGCTs) harbor a somatic FOXL2 c.402C>G mutation in ~95% of cases and are mainly surgically removed due to limited systemic treatment effect." (PMID 32455687, 2020). "The FOXL2 mutation was also detected in 50% of granulosa theca cell tumors, but it is uncommon in juvenile granulosa cell tumors." (PMID 32485873, 2020). "Genomic studies of SCSTs demonstrate that a single somatic mutation in FOXL2 (C134W) is almost ubiquitous in adult granulosa cell tumors, occurring in up to 97% of cases." (PMID 32485873, 2020). "Current research indicates that FOXL2 plays a major role in granulosa cell tumors (GCTs), and the 402C > G mutation in FOXL2 is crucial to the development of adult GCTs." (PMID 31221094, 2019). "Recently, a somatic missense mutation was revealed in the Forkhead box L2 (FOXL2) gene in 97% of adult-type granulosa cell tumors." (PMID 30592193, 2019). "The FOXL2 mutation is maintained in recurrent adult-type granulosa cell tumors of the ovary and represents a very useful marker for the diagnosis of recurrence." (PMID 29389895, 2018). "Although the presence of FOXL2 mutations is almost constantly observed in granulosa cell tumors, some very are granulosa tumors are FOXL2 WT." (PMID 29389895, 2018). "A cornerstone study has demonstrated that nearly all adult granulosa cell tumors (GCTs), a major subtype of sex cord-stromal tumors, harbor a somatic mutation of forkhead box L2 (FOXL2; 402C→G; C134W)." (PMID 29221447, 2017).
granulosa cell tumor (continued). "Recent studies have revealed that FOXL2 gene 402C > G (C134W) mutation plays a key role in the pathogenesis of adult granulosa cell tumor." (PMID 28347324, 2017). "Recent molecular studies have characterized the FOXL2 402C > G mutation in adult granulosa cell tumor." (PMID 28347324, 2017). "Third, we confirmed the high prevalence (5/6; 83%) of pathognomonic mutations in FOXL2 in adult granulosa cell tumors." (PMID 28852190, 2017). "Our previous case report showed that unique FOXL2 402C > G mutation and defective DNA mismatch repair system are associated with the development of adult granulosa cell tumor." (PMID 28347324, 2017). "Of note, a recent study has shown that ~97% of adult granulosa cell tumors carry a FOXL2 somatic missense mutation, highlighting a breakthrough in the field of granulosa cell tumor research." (PMID 27344183, 2016). "Reticulin staining and FOXL2 mutation analysis excluded the possibility of an adult granulosa cell tumor, and the patient was diagnosed with a MACF of the ovary." (PMID 27770806, 2016). "Below, we will discuss the cases of the FOXL2 mutation in adult-type granulosa cell tumors (GCTs) as well as the WTR1-CAMTA1 fusion in epithelioid hemangioendotheliomas (EHEs)." (PMID 25676695, 2015). "We propose that the 402C > G mutation in FOXL2 is critical to the development of adult granulosa cell tumor." (PMID 25297715, 2014). "Recent molecular studies have characterized the FOXL2 402C > G mutation in adult-type granulosa cell tumor." (PMID 25297715, 2014). "Recent studies have shown that FOXL2 402C > G is a diagnostic characteristic of adult-type granulosa cell tumor." (PMID 25297715, 2014). "We report a case of adult-type granulosa cell tumor with FOXL2 402C > G mutation in an 80-year-old woman, in which one allele was normal and one was mutant." (PMID 25297715, 2014). "The nucleotide sequence analysis of FOXL2 from the granulosa cell tumor section revealed heterozygous 402C > G mutation." (PMID 25297715, 2014). "In humans, mutations in the gene that codes for the FOXL2 protein are associated with granulosa cell tumors and with a loss of female fertility in early adulthood." (PMID 25369636, 2014). "Recently 4 granulosa cell tumors were subjected to transcriptome sequencing, revealing a missense G > C mutation at nucleotide 402 of the FOXL2 gene in every case." (PMID 20069115, 2010). "In granulosa cell tumors, the FOXL2 mutations are somatic; in all cases tested, the germline sequence has been normal." (PMID 20069115, 2010). "A somatic mutation in the FOXL2 gene is reported to be present in almost all (97%; 86/89) morphologically defined, adult-type, granulosa-cell tumors (A-GCTs)." (PMID 19956657, 2009). "Thus, molecular pathology plays an important role in the diagnosis of such entities since recurrent alterations have been identified, such as the FOXL2 variant in adult granulosa cell tumors or the CTNNB1 variant in microcystic stromal tumors." (PMID 38136408, 2023). "Therefore, molecular pathology plays an important role in the diagnosis of such entities, with pathognomonic or recurrent alterations, such as FOXL2 variants in adult granulosa cell tumors." (PMID 38136408, 2023). "Mutations in FOXL2 as noted in granulosa cell tumors, therefore, may result in increased androstenedione levels." (PMID 32485873, 2020). "The molecular pathogenesis of granulosa-cell tumors is mainly related to the occurrence of the missense point mutation, 402C→G (C134 W) of the forkhead transcription factor FOXL2, essential granulosa-cell development, observed in 97% of cases of adult type tumors." (PMID 29389895, 2018). "The results of this case study indicated that although FOXL2 402C > G mutation determines the development of granulosa cell tumor, PMS2 mutation may be the initial driver of carcinogenesis." (PMID 28347324, 2017).
granulosa cell tumor (continued). "The results of this case study indicated that although FOXL2 402C > G mutation determines the development of granulosa cell tumor, PMS2 N775L mutation may be the initial driver of carcinogenesis." (PMID 28347324, 2017). "Our hypothesis is that DNA mismatch repair system failure induces FOXL2 402C > G mutation, leading to granulosa cell tumor development." (PMID 28347324, 2017). "Adult-type granulosa cell tumors are associated with FOXL2 402C > G mutation." (PMID 25297715, 2014). "However, we cannot dismiss the possibility that the amino acid changing mutation in FOXL2 402C > G is the driver mutation that leads to subsequent genomic alterations in granulosa cell tumor pathogenesis." (PMID 25297715, 2014). "Our hypothesis is that a DNA repair system failure induces FOXL2 402C > G mutation, followed by granulosa cell tumor development." (PMID 25297715, 2014). "Interestingly, a specific somatic mutation of FOXL2 has been identified in more than 95% of adult-type granulosa cell tumors (GCTs) confirming the strong association of FOXL2 with granulosa cell fate and function." (PMID 25369636, 2014). "Recent studies of FOXL2 (forkhead box L2) gene 402C > G (C134W) mutation may resolve the problems of adult-type granulosa cell tumor diagnosis." (PMID 25297715, 2014). "For instance, mutations in the FOXL2 gene may lead to the formation of granulosa cell tumours." (PMID 39268087, 2024). "The fact that thecomas harboring a FOXL2 somatic variant have been reported to recur in the peritoneum with a typical morphology of an adult granulosa cell tumor indeed suggests that the initial “thecoma” might have represented in fact a luteinized adult granulosa cell tumor." (PMID 38136408, 2023). "Adult granulosa cell tumors, for instance, may carry mutations in the FOXL2 gene." (PMID 37958970, 2023). "However, recent studies have shown that FOXL2 mutation is a defining feature of AGCTs so this is important for future studies, especially those including advanced stage of the disease, which should include only molecularly defined granulosa cell tumors." (PMID 30186737, 2018). "By the same token, if the FOXL2 gene functions to contribute to follicle dormancy and its mutations can cause premature activation of primordial follicles and/or favor the formation of granulosa cell tumors, can other similar factors or the genes do the same in the granulosa cells?" (PMID 29549247, 2018). "Extension of this study by examination of additional cases revealed that these identical 402G->C FOXL2 mutations were present in more than 95% of cases diagnosed as adult-type granulosa cell tumors, as well as occasional thecomas, and a single juvenile granulosa cell tumor (of ten tested)." (PMID 20069115, 2010). "Immunohistochemistry analysis was positive for FOXL2, inhibin, and vimentin, confirming adult granulosa cell tumor classified as International Federation of Gynecology and Obstetrics IC1." (PMID 41137270, 2025). "While most studies examined the role of FOXL2 in granulosa cell tumor pathogenesis and folliculogenesis, the roles of FOXL2 in PCOS and the relationship between AR and FOXL2 in the GCs under hyperandrogenic treatments has not yet been investigated." (PMID 40898340, 2025). "To further determine the molecular identity of tumors observed in TGFBR1CA; Amh-Cre mice, we conducted immunostaining using antibodies against three granulosa cell tumor-expressed protein markers including FOXL2, INHA, and FOXO1." (PMID 38067144, 2023). "In Runx1 KO mice, cells composing the tumors showed an intense expression for FOXL2, indicating that the tumors were granulosa cell tumors." (PMID 36430923, 2022). "A comparative study of miRNA regulation on FOXL2 between adult-type and juvenile-type granulosa cell tumors showed that reduction of the miR-17 family indirectly increased FOXL2 mRNA expression." (PMID 33917022, 2021).
granulosa cell tumor (continued). "Since some adult granulosa cell tumors can be difficult to definitively diagnose based on histology and immunohistochemistry alone, FOXL2 has been suggested for the molecular diagnosis of these tumors." (PMID 32485873, 2020). "The epigenetic dysregulation of central granulosa cell factors such as FOXL2 are involved in the development of granulosa cell tumors, which is possible through EZH2 interaction." (PMID 30087896, 2018). "We confirmed the high prevalence of FOXL2 and KRAS mutations in granulosa cell tumors and in mucinous tumors, respectively." (PMID 28852190, 2017). "At an early age, these mice demonstrated follicular defects and development of ovarian granulosa cell tumors, which were immunoreactive for granulosa cell markers including FOXL2, FOXO1, and INHA." (PMID 29221447, 2017). "The fact that target genes of mutant FOXL2 in granulosa cells are enriched for TGFβ signaling further supports the importance of TGFβ signaling in the pathogenesis of human granulosa cell tumors." (PMID 27344183, 2016). "Adult granulosa cell tumors (GCT) are rare sex cord stromal tumors of the ovary, characterized by distinct histologic features and the near ubiquitous presence of a recurrent somatic mutation in the FOXL2 gene." (PMID 42294120, 2026). "Mutant FOXL2 leads to the pathogenesis of granulosa cell tumor." (PMID 40898340, 2025). "Excluded patients (those without a FOXL2 mutation and therefore possibly representing juvenile granulosa cell tumors) were examined as well." (PMID 38898688, 2024). "In this case, a luteinized adult granulosa cell tumor must be ruled out, using the reticulin stain (fibrils around individual tumor cells in thecomas) and the FOXL2 variant (a variant would favor adult granulosa cell tumor with luteinized foci)." (PMID 38136408, 2023). "In practice, FOXL2 variant testing is not useful since the differential diagnosis is more that of a cellular/mitotically active fibroma rather than a granulosa cell tumor." (PMID 38136408, 2023). "Molecular studies performed on juvenile granulosa cell tumors showed the absence of FOXL2 variant and the presence of DICER1 variants in 6–23% of the cases, sometimes associated with DICER1 syndrome." (PMID 38136408, 2023). "The molecular hallmark of adult granulosa cell tumors is the missense somatic point variant (C402G) of FOXL2, present in >95% of tumor cells, and absent in the juvenile type and in fibromas." (PMID 38136408, 2023). "The FOXL2 402C > G mutation was observed in granulosa cell tumor, but not in the blood or normal tissue." (PMID 28347324, 2017). "Interestingly, the promoter of the FOXL2 gene was found to be hypermethylated in ovary granulosa cell tumors concomitant with increased EZH2 expression." (PMID 28209164, 2017). "This study provides a rich resource of protein interactors colocalizing with FOXL2 on nearby genomic locations that could be used to generate hypotheses on the molecular mechanisms of ovarian development, POI, granulosa cell tumors, and other causes of female infertility." (PMID 38517962, 2024). "Indeed, all cases of SLCT with FOXL2 variants were seen in postmenopausal women with uterine bleeding or estrogenic manifestations, which is not the right clinical setting for SLCT but is reminiscent of clinical symptoms of adult granulosa cell tumors." (PMID 38136408, 2023). "However, the FOXL2 may be wild-type in a subset of adult granulosa cell tumors, especially in the case of an abundant fibromatous background, and in cases with purely cystic patterns." (PMID 38136408, 2023). "Although some SLCTs have been reported with a FOXL2 variant, it is not clear whether these neoplasms could correspond to poorly differentiated/sarcomatoid adult granulosa cell tumors rather than a true SLCT." (PMID 38136408, 2023). "Similarly, a luteinized adult granulosa cell tumor must be ruled out, by searching for the FOXL2 variant." (PMID 38136408, 2023).